KRAS (KRas proto-oncogene, GTPase)
Diseases named in the same sentence as KRAS in open-access papers (continued):
Sharing a sentence is not in itself a finding about the gene and the disease.
Stroke (2 papers, 2016 to 2022). Sudden impairment of blood flow to a part of the brain due to occlusion or rupture of an artery to the brain. "KRAS is one of the TOP 10 hub genes of a stroke gene array, indicating that KRAS may be involved in the occurrence and development of stroke." (PMID 36399471, 2022). "Finally, ESM1, KRAS, miR-181d, miR-181b-3p, miR-605-3p and miR-605-5p were highly expressed in the blood of stroke patients compared to healthy people." (PMID 26830013, 2016). "Five were the targetgenes of let-7 (ESM1, VIM, CDK6, NRAS, and KRAS), 3 of which (ESM1, VIM, and CDK6) were correlated with stroke based on published literatures." (PMID 26830013, 2016).
thoracic tumors (2 papers, 2023 to 2025).
thrombosis (2 papers, 2021 to 2023). "Patients with mutant KRAS had an odds ratio (OR) of 2.758 for VTE compared to KRAS wild-type patients, with an increased risk of thrombosis being maintained in KRAS mutant patients even after adjusting for other known VTE risk factors." (PMID 38069251, 2023). "KRAS mutation was an independent predictor of VTE even after adjustment for other common thrombosis risk factors such as clinical stage, Khorana score, and anti-VEGF agent use." (PMID 38069251, 2023).
thymic carcinoma (2 papers, 2022 to 2025). Thymic carcinoma (TC) is a type of thymic epithelial neoplasm characterized by a high malignant potential.
thymic tumors (2 papers, 2012 to 2021). "Thus, we can confidently hypothesize that the development of thymic tumors, would rely on the expression of mutated KRAS oncogene." (PMID 34302028, 2021).
urothelial papilloma (2 papers, 2020 to 2025). A rare benign condition, characterized by a papillary growth in the urinary tract with a central fibrovascular core. "KRAS mutations are also frequently reported in various papillary or mucinous precursor lesions such as intraductal papillary mucinous neoplasms of the pancreas or urothelial papilloma/carcinomas." (PMID 40860802, 2025).
Warthin tumor (2 papers, 2023 to 2026). An adenoma characterized by an oncocytic, often papillary, epithelial component, dense lymphoid stroma, and cystic spaces. "We herein add a subset of de novo proliferating Warthin tumors to the list of benign salivary gland tumors harboring oncogene (KRAS) mutations." (PMID 36752878, 2023). "In summary, we report for the first time oncogenic KRAS gene mutations, specific to a subset of de novo proliferating Warthin tumor." (PMID 36752878, 2023).
adenofibroma (1 paper, 2016). A benign neoplasm characterized by the presence of connective tissue stroma and epithelial structures. "Sequence analysis revealed no genetic mutations of BRAF or KRAS hotspots, which does not support the hypothesis that mutations of KRAS and BRAF occur at the development of adenofibromas to APSTs." (PMID 27128903, 2016).
adrenal adenoma (1 paper, 2025). "The concurrent diagnosis of a KRAS-driven PRNRP and a TSC/mTOR pathway-associated RCC-FMS, accompanied by an adrenal adenoma, forms a distinctive clinical scenario." (PMID 41367859, 2025).
adrenocortical cancer (1 paper, 2020). "Two of the studies demonstrated that RhoA was negatively associated with AKT phosphorylation and cyclin D1 in both endothelial cells and KRAS-driven adrenocortical cancer cell lines." (PMID 32244355, 2020).
alcohol use disorders (1 paper, 2016). "Conversely, the KRAS T>G polymorphism (rs61764370) showed no consistent association with the presence of ALD or alcohol use disorders." (PMID 27992614, 2016).
alcoholic cirrhosis (1 paper, 2016). "Genotypic and allelic frequencies of the KRAS and RASGRF2 polymorphisms in alcoholic patients vs. controls and in patients with alcoholic cirrhosis vs. patients without alcoholic liver disease." (PMID 27992614, 2016).
ampulla of Vater tumors (1 paper, 2013). "All 4 of the ampulla of Vater tumors showed KRAS mutation, while 7 of 9 IPMN-malignant types harbored mutation." (PMID 23565280, 2013).
anal adenocarcinoma (1 paper, 2018). "As revealed by NGS analysis, a high percentage (47.1%) of anal adenocarcinoma harbored a KRAS mutation." (PMID 29700411, 2018).
anal carcinoma (1 paper, 2014). "In the present study we set out to verify the incidence of KRAS, BRAF and PIK3CA mutations in a series of patients with anal carcinoma and analysed the association between these alterations and the clinical-pathological characteristics of patients." (PMID 24642661, 2014). "Our study shows that KRAS and BRAF are not mutated in anal carcinoma, whereas PIK3CA, mutated in about 20% of cases, may represent a mechanism of resistance to anti-EGFR treatment, such as cetuximab." (PMID 24642661, 2014).
aneurysm (1 paper, 2018). Bulging or ballooning in an area of an artery secondary to arterial wall weakening. "Interestingly, in BAV ECs, several genes involved in WNT/β-catenin and KRAS signaling were up-regulated in response to oscillatory flow, suggesting that these pathways may be of more importance for the development of BAV-related aneurysm." (PMID 29426841, 2018).
apocrine carcinomas (1 paper, 2025).
arthropathy (1 paper, 2024). Any disorder of the joints. "In the colon, it is suggestive that the increased expression of KRAS and RPSA are correlated with a higher risk of UC with arthropathy (OR 1.555, 95%CI 1.134–2.132; OR 2.057, 95%CI 1.161–3.646, respectively)." (PMID 38302916, 2024). "Our results were consistent in that there is a causal relationship between the gene expression and methylation of ARNTL, USP7, KRAS and UC with arthropathy, and can be the potential target of UC with arthropathy." (PMID 38302916, 2024). "IVW-MR analysis also found evidence for the casual association between MTOR, ARNTL, KRAS, and RPSA with UC along with arthropathy ((OR 0.334, 95%CI 0.239–0.467; OR 0.607, 95%CI 0.499–0.739; OR 1.537, 95%CI 1.927–1.980; OR 1.756, 95%CI 1.133–2.724, respectively)." (PMID 38302916, 2024).
atrial septal defect (1 paper, 2021). Interauricular communication is a congenital malformation characterized by a communication between the atrial chambers of the heart. "For example, in the case of atrial septal defect (ASD) and ventricular septal defect (VSD), candidate genes can be counted: NKX2-5, GATA4, TBX20, MYH6, and TBX5, while the pathogenesis of atrioventricular septal defect (AVSD) involves genes, such as PTPN11, KRAS, SOS1, RAF1, and CRELD1." (PMID 34946970, 2021).
B-cell neoplasm (1 paper, 2022). A group of heterogeneous lymphoid tumors generally expressing one or more B-cell antigens or representing malignant transformations of B-lymphocytes. "The improved understanding of genomic variation in mature B cell neoplasms revealed a considerable portion of patients presenting with KRAS or RAS-MAPK pathway aberrations." (PMID 35158933, 2022). "Careful characterization is needed to fully elucidate the meaning of these aberrations in mature B cell neoplasms, also in view of the well-established role of KRAS aberrations in promoting an immunosuppressive and tumor protective microenvironment in the context of solid tumors." (PMID 35158933, 2022). "Thus, in the bustling era for RAS-RAF-MAPK targeting molecules, the KRAS and RAS-MAPK signaling represents a crucial therapeutic target in mature B cell neoplasms that must be completely exploited." (PMID 35158933, 2022). "KRAS mutations and mutations in the RAS-MAPK pathway show heterogeneous incidence among mature B cell neoplasms without apparent association with specific B cell differentiation stages or with specific signaling dependencies (e.g., BCR signaling or microenvironment)." (PMID 35158933, 2022).
benign lung tumors (1 paper, 2018). "Castellano and colleagues reported that PI3K inhibitors cause the regression of KRAS p.G12D-induced benign lung tumors in genetically engineered mouse models." (PMID 29464099, 2018).
Branchioma (1 paper, 2023). A tumor derived from branchial epithelium or branchial rests. "We herein expand on the spectrum of molecular findings in branchioma, in which we detected 5 pathogenic/likely pathogenic gene mutations, particularly two MSH6 mutations, two PTEN mutations, and one KRAS alteration, indicating molecular heterogeneity in branchioma." (PMID 37401932, 2023).
bronchioloalveolar carcinoma (1 paper, 2005). A well or moderately differentiated morphologic variant of lung adenocarcinoma characterized by tumor growth along the alveolar structures without stromal, vascular, or pleural invasion. "However, the incidence of KRAS mutations in the patients treated with erlotinib was low, probably because of the fact that all patients treated with this drug had bronchioloalveolar carcinoma, which rarely has RAS mutations." (PMID 15696205, 2005).
cardia cancer (1 paper, 2021). A malignant neoplasm involving the cardia of stomach.
cardiomyopathy (1 paper, 2020). A disease of the heart muscle or myocardium proper. "In mice, HRAS inserted to KRAS locus can rescue lethal development deficiencies, but results in cardiomyopathy, suggesting non-redundant functions for KRAS." (PMID 32524209, 2020).
cecal adenocarcinomas (1 paper, 2021). "Landau et al64 demonstrated cecal adenocarcinomas have higher levels of KRAS alterations and unfavorable histopathological features, including, notably, TB." (PMID 33792733, 2021).
cecum cancer (1 paper, 2021). "The expression of KRAS wild type, BRAFV600E mutation, and MSI-high was detected in the cecum cancer using molecular pathological examination." (PMID 34406516, 2021). "Furthermore, the expression of KRAS wild type, BRAFV600E mutation, and MSI-high was detected in the cecum cancer using molecular pathological examination with the PCR-reverse sequence-specific oligonucleotide probe method." (PMID 34406516, 2021).
choriocarcinoma (1 paper, 2022). An aggressive malignant tumor arising from trophoblastic cells.
congenital nevus (1 paper, 2021). "KRAS mutation in melanocytic nevi was previously reported in one case of congenital nevus, but no IHC validation was performed." (PMID 34769348, 2021).
conjunctivitis (1 paper, 2012). Inflammation of the conjunctiva of the eye. "Rash (43% vs. 26%), dry skin (45% vs. 36%), conjunctivitis (27% vs. 14%), skin fissures (23% vs. 17%), pruritus (24% vs. 14%), skin toxicity (16% vs. 7%), and erythema (12% vs. 7%) were more common in the WT KRAS group." (PMID 23020584, 2012).
cribriform carcinoma (1 paper, 2023). A carcinoma characterized by the presence of a cribriform architectural pattern. "The frequency of KRAS mutation has been reported to be significantly higher in cribriform carcinoma than in the well-formed glandular type, and a higher frequency of somatic copy number alterations has been reported for cribriform carcinoma than for the well-formed glandular type." (PMID 37053292, 2023).
cutaneous T-cell lymphoma (1 paper, 2025). "Previous work showed that KRAS-induced ERK signaling conferred cell resistance to vorinostat, a histone deacetylase (HDAC) inhibitor and FDA-approved drug for treating cutaneous T-cell lymphoma." (PMID 40796680, 2025).
cystic teratoma (1 paper, 2014). "We present two cases with similarity of primary adenocarcinoma of the gastrointestinal type, harboring KRAS oncogene mutation, likely arising in a mature cystic teratoma of the ovary." (PMID 25297496, 2014).
dental caries (1 paper, 2024). The decay of a tooth, in which it becomes softened, discolored, and/or porous. "There are seven key proteins involved in the action of curcumin on dental caries: MAPK1, BCL2, KRAS, CXCL8, TGFB1, MMP9, and IL1B, all of which spontaneously bind curcumin." (PMID 38920854, 2024).
diabetic retinopathy (1 paper, 2012). "Using Wiki-Pi, we infer that its association to diabetic retinopathy may be mediated through its interactions with the genes HSPB1, KRAS, TMSB4X and DGKD, and that it may be involved in cellular response to external stimuli, cytoskeletal organization and regulation of molecular activity." (PMID 23209562, 2012).
encephalomyelitis (1 paper, 2022). Inflammation of the brain and the spinal cord. "An activating KRAS somatic mutation was found in the patients’ DNA at the time of encephalomyelitis diagnosis." (PMID 35361277, 2022).
esophagitis (1 paper, 2023). An acute or chronic inflammatory disease affecting the esophageal wall. "Cetuximab, in contrast, was an independent predictor for significantly higher toxicity for both non-variant and KRAS-variant patients (OR = 3.42, CI: 1.76–6.67, P = 0.0003), but was not specific to hematologic, pulmonary, or esophagitis." (PMID 37728512, 2023).
familial breast cancer (1 paper, 2012). "Our data do not support the hypothesis that the KRAS variant rs61764370 is implicated in the aetiology of sporadic or of familial breast cancer." (PMID 22436609, 2012).
female infertility (1 paper, 2022). Diminished or absent ability of a female to achieve conception. "Our results suggest that aberrant KRAS/FOXO1/BMP7 signaling in theca cells is likely an important cause of anovulation and female infertility." (PMID 36060690, 2022).
fibrolamellar hepatocellular carcinoma (1 paper, 2021). A distinctive type of liver cell carcinoma that arises in non-cirrhotic livers and is seen predominantly in young patients. "In colorectal and pancreatic cancer, there is one study utilizing a pooled mutant-KRAS peptide vaccine (NCT04117087), and in fibrolamellar hepatocellular carcinoma (FLC), a DNAJB1-PRKACA fusion kinase peptide vaccine (NCT04248569)." (PMID 34063388, 2021).
fragile X syndrome (1 paper, 2022). A genetic syndrome caused by mutations in the FMR1 gene which is responsible for the expression of the fragile X mental retardation 1 protein. "This set of genes included cancer oncogenes (CMYC, CKIT, BCL2, KRAS) and genes associated with different cancer types (ADAM12, ALOX5, SRSF6, VEGF12) as well as FMR1, associated with fragile X syndrome (OMIM: 300624), and SNX12, which is associated with neurodegenerative diseases." (PMID 35573091, 2022).
G6PD deficiency (1 paper, 2025). An X-linked genetic condition caused by alterations in the gene G6PD that result in moderately to severely decreased activity levels of the enzyme glucose-6-phosphate dehydrogenase. "G6PD deficiency impacts insulin signaling activation, while LEPR and KRAS modulate insulin sensitivity and glucose metabolism." (PMID 39823117, 2025).
gallbladder adenoma (1 paper, 2022). A polypoid epithelial neoplasm that arises from the gallbladder. "KRAS mutation was first seen in a gallbladder adenoma of a patient with FAP, suggesting that KRAS mutation may induce malignancy transformation." (PMID 35741793, 2022).
gallbladder tumor (1 paper, 2019). "We tested a series of five shRNA constructs in three gallbladder tumor cell lines expressing ERBB2 with wild type KRAS in OCUG1 cells, along with G415 and NOZ cells harboring the KRAS (G13D) and KRAS (G12V) mutant alleles, respectively." (PMID 30304546, 2019).
gastritis (1 paper, 2025). Inflammation of the stomach. "These genes, modulated in gastritis and GC, influence tumorigenesis‐related pathways such as DNA repair and KRAS signalling, shedding light on GC pathogenesis." (PMID 40012220, 2025).
giardiasis (1 paper, 2024). An infection of the small intestine caused by the flagellated protozoan giardia lamblia. "The mean of KRAS gene expression in people with a history of giardiasis was higher than in healthy people, although the high expression was reported just in the A4 sample." (PMID 38170269, 2024). "The relative expression of the KRAS gene in samples with a history of giardiasis A2 and A8 decreased by 0.75 and 0.65 times, respectively, compared to the average expression of the said gene in healthy individuals." (PMID 38170269, 2024). "Examining the mean expression of the four genes AKT1, CDKN2A, KRAS, and PIK3CA showed that three genes of AKT1, CDKN2A, and KRAS had increased expression in people with a history of giardiasis compared to healthy people." (PMID 38170269, 2024).
gliosarcoma (1 paper, 2023). A rare histological variant of glioblastoma (WHO grade IV) characterized by a biphasic tissue pattern with alternating areas displaying glial and mesenchymal differentiation (WHO). "In this patient’s case, acquired mutations in KRAS with oncogenic potential and NF1 with unknown actionability were observed after prolonged exposure to BRAF inhibition along with a morphological transformation to gliosarcoma." (PMID 37231247, 2023).
heart failure (1 paper, 2022). Inability of the heart to pump blood at an adequate rate to meet tissue metabolic requirements. "Hence, we will further focus on the methylation levels of KRAS, IL10, TLR4 and STAT3, and further determine the risk of heart failure and patient stratification by the combination of methylation and transcriptional expression in the future." (PMID 36324504, 2022).
hemangioma (1 paper, 2021). A benign vascular lesion characterized by the formation of capillary-sized or cavernous vascular channels. "In addition, given the role of KRAS in regulating TSP-1 expression and the association of overexpressed TSP-1 with proliferating hemangioma, it is plausible that targeting the KRAS-mediated pathway might be beneficial." (PMID 33400686, 2021).
hemorrhagic stroke (1 paper, 2021). A stroke caused by a bleed on the brain. "Interestingly, activation of KRAS signaling pathways in the vascular endothelium has also been recognized to induce brain vascular malformations and hemorrhagic stroke." (PMID 34307198, 2021).
Hepatic steatosis (1 paper, 2021). Steatosis is a term used to denote lipid accumulation within hepatocytes. "In addition to hepatic steatosis, number of liver metastasis, preoperative chemotherapy, and KRAS mutation were also identified as significant predictors of hepatic RFS." (PMID 33767997, 2021).
hepatoid adenocarcinoma (1 paper, 2025). An adenocarcinoma with morphologic characteristics similar to hepatocellular carcinoma, arising from an anatomic site other than the liver. "Future investigations involving more cases will be essential to comprehensively understand the significance of KRAS mutations in hepatoid adenocarcinoma." (PMID 40161114, 2025).